NRP1 (neuropilin 1)
Diseases named in the same sentence as NRP1 in open-access papers (continued):
Sharing a sentence is not in itself a finding about the gene and the disease.
cancer (continued). "In addition, the increased survival of PDAC patients whose tumors contain trans‐complexes shows the clinical relevance of the interaction of VEGFR2 and NRP1 in cancer." (PMID 30027561, 2018). "As such, it seems plausible that therapies that target NRP‐1 to control various cancer‐related events might even be more effective due to its additional ability to overcome chemoresistance." (PMID 30216699, 2018). "Interestingly, the in vitro enrichment of cancer stem cells induced a NRP-1 overexpression for all cell lines, which is encouraging to consider NRP-1 targeting as a strategy applicable to different MB subgroups." (PMID 29632646, 2018). "An improved response to anti‐angiogenic therapy in cancer types with low NRP1 expression could be dependent on the preferential formation of VEGFR2/NRP1 cis‐complexes within the endothelium, promoting angiogenesis, which would be blocked by bevacizumab." (PMID 30027561, 2018). "It remains to be seen if NRP1-expressing CD8+ T cells in cancer represent exhausted CD8+ cells." (PMID 29067024, 2017). "In GBM, semaphorin3A (Sema3A)-NRP1 signaling mediates the invasion of cancer cells." (PMID 29088765, 2017). "We have also previously shown that NRP1 promoted an undifferentiated phenotype in cancer cells." (PMID 29018205, 2017). "Currently, modified expression of VEGF receptors (VEGFR1, VEGFR2, or NRP1) appears to be among the most promising markers for bevacizumab treatment, though this has not consistently been replicated across different studies involving various cancer types." (PMID 29267273, 2017). "However, several groups have reported NRP1-expressing Tregs in humans under different pathological conditions, including cancer, as discussed later in this section." (PMID 29067024, 2017). "In recent years, NRP1 overexpression has been reported in many diseases including cancers." (PMID 29088765, 2017). "Finally, VEGF plays a dual role in skin cancer by stimulating angiogenesis through a paracrine mechanism by signalling via VEGFR2 and by promoting cancer stem cell renewal through an autocrine, NRP1-dependent mechanism." (PMID 26923176, 2016). "NRP1 has been demonstrated to be a potential target in cancer therapies." (PMID 27863391, 2016). "In recent years, several types of mouse knockout models have been developed that have provided useful tools for experimental investigation of NRP1 function, and a multitude of therapeutics targeting NRP1 have been designed, mostly with the view to explore them for cancer treatment." (PMID 26923176, 2016). "Moreover, NRP-1 knockdown significantly affected the growth kinetics of BxPC-3 cancer cells in vitro as observed by the MTT assay for cell viability." (PMID 27542226, 2016). "We further tested whether LKB1-mediated abrogation of NRP-1 correlated with reduced metastatic potential within cancer cells." (PMID 26701889, 2016). "Several studies have examined the role of glycosylated NRP1 in cancer." (PMID 26755661, 2016). "In the case of cancer, such complexes may form in the circulation, because these patients have significantly elevated levels of circulating truncated NRP1." (PMID 27486976, 2016). "The knockdown of VEGF-A or NRP1 abrogated the proliferation of these cancer cells." (PMID 26209534, 2015). "NRP1 has therefore been identified as an attractive therapeutic target for various cancers." (PMID 26097868, 2015). "The inhibition of VEGF-A/NRP1 signaling may represent a new strategy against cancer and be applied in the design of new cancer drugs." (PMID 26209534, 2015). "Nevertheless, our findings suggest immunohistochemistry for FOXP1/NRP1/cyclin D1 may be useful, in conjunction with family history, in selecting patients with basal cancers for BRCA1 screening." (PMID 26152113, 2015).
cancer (continued). "While reporting mostly negative data, our findings have therapeutic implications, as Nrp1 is now being targeted for human cancer therapy in clinical trials, but the precise molecular pathways and immune cells being engaged during treatment remain incompletely defined." (PMID 25343644, 2014). "Recent studies have also revealed an important role of NRP-1 malignant progression of many cancers." (PMID 25333267, 2014). "To assess a potential role for Nrp1 in CD8+ T cell function under these conditions, we evaluated the ability of Nrp1-deficient T cells to provide effective adoptive T cell immunotherapy for cancer." (PMID 25343644, 2014). "Numerous reports indicate that NRP1 may serve as a potential prognostic biomarker and a valuable therapeutic target for a variety of human cancers." (PMID 24999732, 2014). "Moreover peptides targeting and inhibiting the TM of NRP1 turn out to be very potent anti-cancer drug contributing to the identification of NRP1 as a major therapeutic target in cancer." (PMID 24858828, 2014). "In addition to its function in neural and vascular development, NRP1 expression has been detected in various human cancers such as prostate carcinoma, pancreatic carcinoma, astrocytic tumors, and OSCC." (PMID 24999732, 2014). "VEGF and its receptor proteins—including one called NRP1—are being investigated as a possible target for drugs that could treat cancer and other diseases affecting blood vessels." (PMID 25244320, 2014). "Since cancer cells frequently express Nrp1, it could be a target permitting internalization of many drugs into these cells." (PMID 22948112, 2012). "They concluded that Nrp1 promotes an undifferentiated phenotype in cancer cells." (PMID 22948112, 2012). "We found that Nrp1+ T cells and cancer cells have an increased ability to capture LAP-TGF-β1." (PMID 22948112, 2012). "Moreover, NRP1 associates with TGFRI and TGFRII to enhance TGFβ1 signaling in cancer cells, augmenting canonical Smad2/3 signaling." (PMID 21747928, 2011). "Furthermore, NRP1 antagonism enhanced the inhibitory effect of function-blocking integrin-β1 antibody on carcinoma cell adhesion to ECM, indicating that NRP1 synergistically cooperates with integrin-β1 to promote carcinoma cell adhesion to matrix proteins." (PMID 20087344, 2010). "A549 and ACHN carcinoma cells also expressed NRP2 at a level similar to that of NRP1." (PMID 20087344, 2010). "It has been suggested that NRP1 predominantly expresses in carcinoma cell lines (epithelial origin), including carcinomas of lung, breast, prostate, pancreas, and colon, whereas NRP2 is frequently present in non-carcinoma cell lines derived from melanoma, leukaemia, and neuroblastoma." (PMID 20087344, 2010). "In this study we used a specific antagonist of VEGF binding to the NRP1 b1 domain, EG3287, to investigate the functional roles of NRP1 in human carcinoma cell lines, non-small-cell lung A549, kidney ACHN, and prostate DU145 cells expressing NRP1, and the underlying mechanisms involved." (PMID 20087344, 2010). "Notably, uPA (PLAU) and NRP-1 transcripts are significantly upregulated across most cancer types." (PMID 41436559, 2025). "Furthermore, NGF may attach to the membrane receptor sortilin, which has been demonstrated to participate in cancer growth, and also to neuropilin-1 (NRP1), a nociceptor-enriched co-receptor for NGF that is necessary for the TrkA signaling of pain." (PMID 38392180, 2024). "Therefore, NRP1-targeting peptide can effectively penetrate deep into tumors to treat cancers." (PMID 38255307, 2024). "Thus, the CD was used to test the impact on NRP1 expressions in human cancer cell lines." (PMID 38138098, 2023). "Current evidence also indicates that inhibiting NRP1 activity through any of the different possible approaches, from small molecule-mediated inhibition to RNA interference knockdown, can display antitumor effects in several cancer types and across a range of experimental models and conditions." (PMID 37894289, 2023).
cancer (continued). "Consequently, Nrp-1 has been proposed as an immune checkpoint molecule on CD8+ T cells in cancer." (PMID 38019895, 2023). "NRP1 expression may be a marker of poor prognosis in different cancer types." (PMID 37894289, 2023). "In this regard, the presence of ACE2 receptors and NRP-1 in different tissues could be beneficially seen as a prognostic marker in patients with certain cancer types and in favor of the usage of SARS-CoV-2 as an oncolytic agent, which will be discussed in a later section of this review." (PMID 36768649, 2023). "Therefore, NRP1 functioned as an unfavorable prognostic marker in most cancer types." (PMID 36338984, 2022). "Consequently, NRP-1 is considered a potential target for cancer therapy." (PMID 33884469, 2021). "It was found in the LncTarD database that CYTOR functioned as a competing endogenous RNA (ceRNA) to positively regulate NRP1 expression by sponging with miRNA-206, which could positively affect epithelial to mesenchymal transition, cancer progression, and cell growth." (PMID 33749514, 2021). "Given the substantial resources invested in NRP1-targeted anti-angiogenesis therapies for cancer, our results will provide new insights into the regulate mechanisms of NRP1 related angiogenesis and ultimately may be integral for developing new treatment strategies." (PMID 34150622, 2021). "Interestingly, NRP1 also plays an important role in cellular immunity, whether in physiological or pathophysiological conditions, such as cancer." (PMID 34277411, 2021). "Therefore, NRP-1 has been put forward as an interesting target to manage cancer." (PMID 33266104, 2020). "Therefore, targeting NRP‐1 has been shown to be a potential therapeutic target for some cancers." (PMID 32951327, 2020). "Furthermore, our results suggest that Nrp-1 expression on CD8+ TIL could be used as a potential biomarker to predict response to anti-PD-1 treatment of cancer patients." (PMID 31350404, 2019). "However, in patients with certain advanced stage cancers, such as pancreatic adenocarcinoma and colorectal cancer, Nrp1 expressing T cells are significantly elevated in their blood and have been considered as potential biomarkers for their degree of immunosuppression in these patients." (PMID 32914058, 2018). "Moreover, NRP-1 seems to favor an undifferentiated phenotype in cancer cells." (PMID 29632646, 2018). "Thereby, it was assumed that NRP1 might constitute a promising target for cancer therapy." (PMID 29018205, 2017). "Therefore, the experimental data on the role of NRP1 in cancer are conflicting, and the molecular mechanisms of differential role of NRP1 in tumorigenesis remain unknown." (PMID 29018205, 2017). "Furthermore, these findings may help to guide the on-going efforts to develop drugs that target NRP1 into treatments that are effective against diseases that involve problems with blood vessels—including diabetes, immune disorders, and cancer." (PMID 25244320, 2014). "Since the integrin β1-subunit mediates specific cell binding to laminin, collagen, and fibronectin, and has been shown to be a major integrin receptor expressed in carcinoma cells, we evaluated whether there was possible cooperation of NRP1 with integrin-β1 in carcinoma cell–matrix adhesion." (PMID 20087344, 2010). "The functional divergence between NRP1+ and NRP2+ TAMs reflects the cancer type-specific heterogeneity and highlights their specialized roles in modulating the TME." (PMID 40134439, 2025). "Further, Gal-1 influences cancer biology by promoting and regulating angiogenesis through the VEGFR2/NRP1 glycan binding signaling pathway and regulation of alternative splicing, and metastasis, priming pre-metastatic niches." (PMID 41918780, 2025). "The pro/anti-angiogenic function of NRP1 shows a novel pathway in cancer metastasis mediated by KRAS and TGF-β signaling through NRP1." (PMID 40277760, 2025).
cancer (continued). "VEGFA ligand expressed on epithelial cells (cancer cells and AT1 cells) communicated with FLT1 (VEGF receptor 1), KDR (VEGF receptor 2), and NRP1 (a coreceptor for KDR) expressed on ECs99." (PMID 39803458, 2025). "The overexpression of NRP1 and GLUT1 in various tumors makes them promising targets for accurate cancer diagnosis." (PMID 40048021, 2025). "Therefore, NRP-1 may serve as a potential target for gene therapy in the treatment of this cancer." (PMID 40430075, 2025). "By using sc-RNAseq, this paper highlights the inter- and intra-tumoural heterogeneity of NRP1 and NRP2 expressions across different cell types in different cancer types, namely ccRCC and SKCM where each of the isoforms were distinctively highest." (PMID 40134439, 2025). "Cancer cells are defined as cells expressing high MKI67, CAV1, and CTNNB1 and present spatial variations in the expression of VEGFC, FN1, and NRP1." (PMID 40081369, 2025). "The nuanced roles of neuropilin (NRP) isoforms, NRP1 and NRP2, have attracted considerable scientific interest regarding cancer progression." (PMID 40134439, 2025). "In addition to ACE2, other membrane proteins may act as Spike receptors (or co-receptors) for SARS-CoV2 among which we only mention AXL, Neuropilin-1, and CD147 that are highly expressed on cancer cells and might explain the increased susceptibility of cancer patients to infection." (PMID 41375068, 2025). "Furthermore, in multiple cancer types, CD93 expression positively correlates with the expression of various immune checkpoint molecules, including CD86, leukocyte-associated immunoglobulin-like receptor 1 (LAIR1), V-set immunoregulatory receptor (VSIR), and neuropilin 1 (NRP1)." (PMID 40943530, 2025). "Prior to investigating the targeting specificity of the probe, we evaluated the expression of NRP1 and GLUT1 in various cancer cells." (PMID 40048021, 2025). "Heatmap results showed that NRP1, MFAP2, KLC1, DST, and MYOZ3 were generally downregulated in cancer cell lines, while KIF21B, SRI, INCENP, and KEAP1 were also downregulated." (PMID 40228435, 2025). "VEGFA maintains cancer stemness and progression of TNBC through the NRP-1/GAPVD1 axis and Wnt/β-catenin signaling pathway." (PMID 38169627, 2024). "Whereas this evidence supports a widespread role of NRP1 as a positive regulator of TGF-β in mesenchymal, immune and cancer cells, in ECs NRP1 acts as a negative regulator of TGF-β signalling." (PMID 38323651, 2024). "Collectively, these data showed that the VEGFA/NRP-1/GAPVD1 axis is involved in the regulation of cancer stemness and mobility in TNBC cells and that GAPVD1 acts as an effector downstream of NRP-1 in this process." (PMID 38169627, 2024). "Because of its promising anti-cancer properties, EG00229 served as a lead compound to develop new NRP1 inhibitors such as EG01377." (PMID 38323651, 2024). "The surprising opposing roles of NRP1 in the regulation of TGF-β signalling in ECs versus smooth muscle, cardiomyocytes, immune and cancer cells remain to be fully elucidated." (PMID 38323651, 2024). "The combination of NRP1-interfering molecules with MET-targeted drugs enhanced their effectiveness and prevented, or even reversed, the development of resistance in cancer cells and tumor models." (PMID 39769452, 2024). "Neuropilin-1 (NRP1) is a transmembrane glycoprotein that contributes to the growth and metastasis of cancer cells by acting as a multifunctional co-receptor and engaging with various signaling pathways." (PMID 39769452, 2024). "The most recent molecular target suggested for CTX is Neuropilin-1 (NRP-1), a vascular endothelial growth factor (VEGF) known to be overexpressed in many cancers but naturally upregulated in normal lung and heart tissues." (PMID 37444498, 2023). "Previous studies find the correlation between PDIA3 and NRP1, CD276 was also very significant in pan-cancer." (PMID 37251370, 2023).
cancer (continued). "It is well-known that NRP1 is expressed in normal kidney tubule tissue, KIRC, and KIRP, implying a possible target for budding therapeutics in cancers." (PMID 38138098, 2023). "The GAG glycosylation of NRP1 at Ser612 plays an important role in the modulation of VEGF signaling, cell proliferation and migration, and cancer invasion." (PMID 37108554, 2023). "For lymphoid immune cells, the expression of NRP1 was negatively correlated with the infiltration of B and T helper (Th) 1 cells, CD4+T central memory (Tcm), and NKT cells in almost all cancers, and NRP2 presented similar results." (PMID 37190154, 2023). "And especially, USP28 was significantly correlated with NRP1, CD276, ADORA2A, and TNFSF15 in most cancers." (PMID 37450415, 2023). "Thus, CD may be a therapeutic component for SARS-CoV-2 and cancers by at least targeting NRP1." (PMID 38138098, 2023). "In most TCGA cancers, except for SARC and TGCT, there was a strong positive correlation between USP28 and CD276 and Neuropilin-1 (NRP1)." (PMID 37450415, 2023). "This correlation was not due to immune or stromal cell infiltration in claudin-low tumors, as NRP1 expression correlated with a ‘core’ claudin-low signature enriched in EMT and cancer stem cell markers that characterize the claudin-low subtype." (PMID 35078508, 2022). "According to the correlation analysis between SRSF3 and immune checkpoint gene expression, it can be found that SRSF3 is closely related to TNFSF14, TNFRSF14, TNFRSF25, CD276, NRP1, VSIR in a variety of malignant tumors (P <0.05)." (PMID 35494088, 2022). "Correlation analysis of FDX1 with checkpoint gene expression found a high correlation (p < 0.05) with tumor necrosis factor (TNF)–related immune genes (TNFRSF14, 15, 25) and CTLA4, PDCD1, CD274, NRP1, and VTCN1 in some kinds of cancers." (PMID 36061184, 2022). "NRP1 inhibition with a novel peptidomimetic agent, MR438, was evaluated with radiotherapy (RT) in MB models (DAOY, D283-Med and D341-Med) in vitro on cancer stem-like cells as well as in vivo on heterotopic and orthotopic xenografts." (PMID 36457009, 2022). "Given the importance of R373 for neuropilin-1 recognition, the cleavage of CgA1-373 to form CgA1-372 may represent an important mechanism to limit the CgA1-373 activity at the site of its production (for example, in cancer lesions) and to avoid systemic effects." (PMID 36559048, 2022). "Angiogenesis inhibitors, such as bevacizumab, can face resistance from cancer cells that involves alteration of VEGF tyrosine kinase receptors (VEGFR) and binding with Neuropilin-1 (NP1) and/or Neuropilin-2 (NP2)." (PMID 35163777, 2022). "In most cancer types, CD274 (PD-L1), NRP1, and TNFSF15 were positively correlated with YAP1 expression." (PMID 36479120, 2022). "We also predicted and confirmed the effect of NRP1 on the activity of MAPK signaling and the dysregulation of genes involved in molecular mechanisms of cancer pathways." (PMID 34249735, 2021). "On the other hand, IGF-1R expression positively correlates with the expression of NRP1 and CD276 in the majority of 33 cancer types." (PMID 34804946, 2021). "Neuropilin-1 (NRP1, BDCA-4) induces a c-Jun N-terminal kinase (JNK)-dependent signaling cascade that leads to the upregulation of EGFR or IGF1R, thereby promoting cancer cell growth." (PMID 33732282, 2021). "In fact, NRP-1 can lead to cisplatin-induced EGFR phosphorylation, an escape mechanism activated by cancer cells upon cytotoxic stress." (PMID 34359721, 2021). "Therefore, NRP1 may serve as a target for new therapeutic strategies to treat BC and other cancers." (PMID 34249735, 2021). "Specifically, the TCGA datasets were integrated to evaluate the correlations of LATS2 expression with the four specific immune cell gene markers (PTPRC, BCL6, NRP1, and THBD) in 33 cancer types." (PMID 34699318, 2021).